MTBP (MDM2 binding protein)
Diseases named in the same sentence as MTBP in open-access papers (continued):
Sharing a sentence is not in itself a finding about the gene and the disease.
cancer (continued). "MTBP (MDM2 binding protein) has been regarded as a novel pro-oncogene of human cancer cells." (PMID 36106099, 2022). "Thus, further investigation is needed to flesh out these different roles of MTBP in cancer proliferation and metastasis." (PMID 35741402, 2022). "Therefore, although the delay in lymphoma development with Mtbp heterozygosity indicates Mtbp has a role in cancer, the field was left with a fundamental question: What is the function of MTBP?" (PMID 35741402, 2022). "Moreover, publicly available data indicate MTBP mRNA is overexpressed in multiple human cancers including breast, cervical, colorectal, gastric, lung, prostate, and squamous cell carcinoma of the skin." (PMID 35741402, 2022). "Therefore, further investigation of MTBP in cancer and development of therapies targeting it are potentially beneficial and warranted." (PMID 35741402, 2022). "MTBP could promote human cancer cells’ proliferation or metastasis by functioning as a co-activator of c-MYC (cellular-myelocytomatosis viral oncogene) or ZEB2 (Zinc Finger E-Box Binding Homeobox 2)." (PMID 34249768, 2021). "A compelling hypothesis is that MTBP may also regulate p-Erk nuclear import in multiple types of cancer cells." (PMID 29765550, 2018). "Further investigation into the specific amino acids responsible for the binding of MTBP to Tip48/Tip49 as well as crystallization of this structure may allow for development of potential therapeutics to target MTBP in cancer, as has been accomplished with other MYC cofactors." (PMID 35741402, 2022). "Moreover, given the prominent role of the C-terminus of MTBP in regulating DNA replication, this approach to targeting MTBP may further inhibit the rapid rate of DNA replication in cancer cells, essential for cancer cell proliferation." (PMID 35741402, 2022). "However, further testing is required to define the full spectrum of cancers that might benefit from therapies directed against MTBP." (PMID 35741402, 2022). "Additionally, we will discuss the inhibition of cancer cell growth and induction of cancer cell death by decreasing MTBP levels, indicating MTBP may represent a new cancer drug target and a way of indirectly targeting MYC." (PMID 35741402, 2022). "Thus, the role of MTBP in cancer progression appears to be dependent on cellular context." (PMID 29765550, 2018). "The results from the MtbpH/− mice and MEFs corroborated with the previously reported inhibitory roles of MTBP in HCC progression and migration using human cancer cell lines, showing the significance and usefulness of the MtbpH/− mice." (PMID 37760565, 2023). "MDM2-binding protein (MTBP) is the transcriptional target of MYC oncogene, found to be overexpressed in various cancers including TNBC." (PMID 37174125, 2023). "Despite these observations, the regulatory mechanism for MTBP in human cancer has not yet been fully elucidated." (PMID 38009308, 2023). "Given the function of MTBP in proliferation, DNA replication, and cellular transformation as well as the connection between MTBP and MYC, it would be expected that MTBP has a critical role in cancer." (PMID 35741402, 2022). "While in some situations this increased expression of MTBP may be due to the high proliferative state in these cancers and/or MYC dysregulation, the MTBP gene undergoes amplification in multiple cancers." (PMID 35741402, 2022). "Moreover, suppression of MTBP expression in malignant cells or expression of a mutant with apparent dominant-negative activity demonstrated MTBP-directed therapeutics could have broad applicability as cancer therapies and extending patient survival, similar to its binding partner MYC." (PMID 35741402, 2022). "Such migration-suppressive function of MTBP may be mediated by the cytoplasmic portion of MTBP, since a nuclear localization signal (NLS) mutant MTBP, localizing to the cytoplasm, retains the ability to inhibit cancer cell migration." (PMID 37760565, 2023).
cancer (continued). "In addition to the inhibitory function on cell migration and cancer metastasis, MTBP has also been proposed to play roles in origin firing for DNA replication, mitotic progression, MDM2 stabilization, regulation of Myc, and promotion of cancer progression." (PMID 37760565, 2023).
tumor (12 papers, 2015 to 2024). "Moreover, reduced MTBP expression has been linked to increased invasion and migration of tumor cells in culture and metastasis in mouse models." (PMID 35741402, 2022). "In addition, an analysis of lncRNA-mRNA co-expression indicated that lncRNA is related to ROR2 and MTBP genes, which are tumor-associated protein-coding genes." (PMID 30766487, 2019). "Interestingly, there was a significant association between high expression of MTBP and cytoplasmic localization of p-Erk after controlling for tumor location (p-value from exact logistic regression=0.034)." (PMID 29765550, 2018). "TOPBP1 and CDC45 play an important role in DNA replication, and MTBP plays a critical role in promoting the growth and migration of tumor cells." (PMID 37266876, 2024). "Significantly, depletion of MTBP hindered cell proliferation, migration, and invasion induced by overexpressing C9orf142, as well as suppressed tumour growth and lung metastasis in mice." (PMID 38009308, 2023). "Functional rescue experiment demonstrated that knockdown of MTBP attenuated C9orf142‐mediated tumour growth and metastasis." (PMID 38009308, 2023). "In the xenograft tumour mouse models, the C9orf142‐mediated enhancement of tumour growth was partially impaired after MTBP knockdown." (PMID 38009308, 2023). "MTBP was highly expressed in HCC clinical specimens compared to those of the paired non-tumor tissues." (PMID 34249768, 2021). "The results presented in indicate that MTBP silencing in GF-1712 and U87 GSCs significantly inhibits intracranial tumor growth and prolongs survival time (P<0.001)." (PMID 31534534, 2019). "MTBP was diffusively located to both the cytoplasm and the nucleus in non-tumor liver and HCC tissues, while the staining patterns of p-Erk were diverse where some were localized to the nucleus and others were mainly in the cytoplasm." (PMID 29765550, 2018). "In either case, the results from the MtbpH/− mice support the tumor-suppressive role of MTBP." (PMID 37760565, 2023). "MTBP has also been found to act as a tumor suppressor in some cases." (PMID 34249768, 2021). "In addition, the overexpression of MTBP in GS-1802 GSCs enhances in vivo tumor growth and reduces survival time (P=0.014)." (PMID 31534534, 2019). "Moreover, combination of MTBP inhibition with radiation or TMZ treatment showed a further reduction in tumor growth, and significantly prolonged mouse survival (Log-rank P<0.05)." (PMID 31534534, 2019). "We could not detect significant association of levels of MTBP or p-Erk with tumor size or pathological grade of primary HCC." (PMID 29765550, 2018). "A total of 76 mRNAs was correlated to lncRNA NR_046683, including ROR2, MTBP and ATP2C2, which are tumor-related protein-coding genes." (PMID 30766487, 2019). "Consistent with our previous report, overall MTBP levels were significantly lower in both primary and metastatic HCC tumors when compared with non-tumor liver tissues, although there were some HCC tissues showing moderately high levels of MTBP." (PMID 29765550, 2018). "Notably, MTBP is highly expressed in TNBC patients and plays a critical role in promoting tumour growth, survival and resistance to anticancer agents." (PMID 38009308, 2023). "The overexpression of MTBP in MHCC97-L cells accelerated the elimination of sorafenib in HCC cells and the subcutaneous tumor tissues, and the half-life time (t1/2 values) of sorafenib in HCC cells or tumor tissues was significantly reduced." (PMID 34249768, 2021). "The knockdown of MTBP in MHCC97-H cells accelerated the elimination of sorafenib in HCC cells or the subcutaneous tumor tissues, and the half-life time (t1/2 values) of sorafenib in HCC cells or tumor tissues was significantly reduced." (PMID 34249768, 2021).
tumor (continued). "Because MTBP promotes pro-proliferative MYC-dependent transcriptional activity and limits MYC-induced apoptosis in untransformed cells, these may provide cells with sufficient time to disable the effects of tumor suppressors that otherwise restrain MYC-mediated cellular transformation." (PMID 35741402, 2022). "To investigate correlation between MTBP levels and p-Erk subcellular localization in human HCC tissues, we performed immunohistochemistry (IHC) for MTBP and p-Erk using paraffin embedded non-tumor liver and HCC tissues, comprising 10 non-tumor liver, 57 primary HCC, and 36 metastatic HCC tissues." (PMID 29765550, 2018).
MTBP also shares sentences with these, for which no sentence is quoted: gastric cancer (2 papers); head and neck cancer (1); infection (1); neurodegenerative disease (1); nicotine dependence (1); Obesity (1); ovarian carcinoma (1); sarcoma (1).